TLR4 (toll like receptor 4)
Diseases named in the same sentence as TLR4 in open-access papers (continued):
Sharing a sentence is not in itself a finding about the gene and the disease.
metabolic disorders (continued). "Our findings suggest that targeting TLR4‐IRE1α pathway can be a potential therapeutic choice for the treatment of NAFLD as well as other metabolic disorders, with lipotoxicity being the principal pathomechanism." (PMID 29673059, 2018). "LPS and saturated fatty acids can activate Toll-like receptor 4 (TLR4) signaling pathways to drive systemic inflammation and metabolic disease." (PMID 29143791, 2017). "Involvement of toll-like receptor 4 (TLR4) signaling in the pathogenesis of metabolic disorders has been well documented." (PMID 26921251, 2016). "This is supported by recent studies, which have provided strong evidence that TLR4 signaling not only mediates myocardial inflammation and ischemic injury but also contributes to cardiac dysfunction during metabolic disease." (PMID 25101057, 2014). "The relevance of TLR4 pathways for metabolic disease was confirmed by the finding that the deletion of Tlr4 prevented high-fat diet-induced IR." (PMID 24278677, 2012). "As saturated fatty acids-induced activation of TLR4 is involved in enhancing metabolic disease, we expected that MyD88 would exacerbate metabolic disease." (PMID 20824098, 2010). "There is ongoing research of more selective TLR4 inhibitors (lipid A analogs, small molecules) that, along with microbiota-directed therapies, could be investigated for application in metabolic disease." (PMID 41459531, 2025). "Additionally, TLR4 expression has been found to be positively correlated with LPS‐producing bacteria and negatively correlated with prebiotics in numerous metabolic disease models." (PMID 39073297, 2024). "Inhibiting the expression of related inflammatory factors by blocking the TLR4 signaling pathway may have a preventive effect on metabolic diseases." (PMID 38275739, 2024). "Finally, correlation analysis revealed a surprising finding that GC effectively targets the Akkermansia-TLR4/Myd88/NF-κB pathway axis to ameliorate glycolipid metabolism disorders." (PMID 38539827, 2024). "With the high levels of ROS and lower levels of SOD2 detected in TLR4/NF-κB-activated trophoblasts, our data further elucidated that the TLR4/NF-κB-induced metabolic disorders might inextricably link with the redox disturbances in the PE placentas." (PMID 34804360, 2021). "In this clinical context, the pharmacological blockade of TLR4 or the NLRP3/IL-1β/IL-1 receptor axis may provide a therapeutic strategy for preventing and/or treating the vascular alterations associated to metabolic diseases." (PMID 32214150, 2020). "Bacterial endotoxin, circulating levels of which increase during metabolic diseases that exhibit metabolic endotoxemia, readily promotes adipose tissue inflammation by activating toll-like receptor 4 (TLR4), which is highly expressed in adipocytes as well as macrophages." (PMID 32158768, 2020). "Therefore, FxOH probably regulates TLR4 signaling of macrophages and recovers chronic inflammation in adipocyte cells induced by metabolic disorder." (PMID 26248075, 2015). "Therefore, carotenoids in paprika probably suppressed activation of NF-κB, regulated TLR4 signaling of macrophages, and recovered chronic inflammation in adipocyte cells induced by metabolic disorder." (PMID 24049664, 2013). "Interestingly, inhibiting TLR-4 expression has been shown to improve LPS-induced IR, suggesting that targeting TLR-4 may hold therapeutic potential for managing LPS-related metabolic disorders." (PMID 40177494, 2025). "In a separate study on proteomic contents of sEV, absence of toll-like receptor 4 (TLR4) was observed in plasma sEV derived from dairy cows with high-risk to metabolic diseases in contrast to unique presence of TLR4 in plasma sEV derived from dairy cows with low-risk to metabolic diseases." (PMID 37012302, 2023). "Interestingly, recent findings suggest that PG could have an anti-inflammatory effect by inhibiting toll-like receptor-4 involved in the development of low-grade metabolic diseases." (PMID 36362012, 2022).
metabolic disorders (continued). "These previous and current findings, taken together, suggest that GM3 species act as TLR4‐selective endogenous modulators to induce receptor dimerization/ oligomerization, and consequently enhance signal transduction leading to chronic inflammation in metabolic disorders." (PMID 32378734, 2020). "LPS interacts with toll-like receptor (TLR)-4 through binding to the co-receptor myeloid differentiation protein-2 (MD-2), resulting in downstream inflammatory events, which may be responsible for the development of metabolic diseases." (PMID 25923657, 2015). "This includes signaling through toll-like receptors (TLRs), among which activation of TLR4 expressed in innate immune cells plays a key role in HFD-induced hypothalamic inflammation and metabolic disease." (PMID 33741533, 2021). "Saturated fatty acids and LPS activate toll-like receptor 4 (TLR4) signaling pathways further contribute to promoting systemic inflammation and consequent metabolic disorders." (PMID 32531935, 2020). "Lipopolysaccharide is the classical ligand for TLR4, although free fatty acids (FFAs) are also thought to be key activators of TLR signaling during metabolic disease." (PMID 25101057, 2014). "However, the intracellular mechanisms of TLR4-mediated metabolic disease are unknown." (PMID 20824098, 2010). "Rodents with pharmacological inhibition and knockdown of TLR4 as well as neuronal deletion of the TLR adaptor molecule myeloid differentiation primary response 88 (MyD88) are protected from HFD-induced leptin resistance and metabolic disorders." (PMID 33741533, 2021). "The high concentration of LPS in circulation activates Toll-like receptors 4 (TLR-4) and nucleotide-binding oligomerization domain (NOD) expression and initiates low-grade inflammation, which ultimately contributes to obesity and development of metabolic disorders." (PMID 32326604, 2020). "GF TLR4−/− C3H/HeN mice colonized by B29, however, did not develop any NAFLD or other metabolic disease features not seen in noncolonized controls." (PMID 32019793, 2020). "This suggests that resistin may act through TLR-4 and not CAP1 during Nb infection, and the importance of CAP1 in resistin-mediated effects may be more significant in metabolic disorders." (PMID 25568944, 2015).
neurodegenerative disease (83 papers, 2006 to 2026). A disorder of the central nervous system characterized by gradual and progressive loss of neural tissue and neurologic function. "Inhibition of TLR4 signaling reduces the risk of neurodegenerative diseases, and up-regulation of anti-inflammatory cytokines associated with LPS hyperresponsiveness can have adverse effects in the brain." (PMID 38001534, 2023). "Several studies have reported that drugs that reduce proinflammatory cytokine levels in vitro and in vivo via TLR4-dependent signaling pathways hold potential for treating neuroinflammation-linked neurodegenerative diseases." (PMID 35841100, 2022). "The TLR4, a pattern recognition immune receptor, has been implicated in neurodegenerative disease-related neuroinflammation." (PMID 34777683, 2021). "Abnormal TLR4 expression has been implicated in impaired microglial functioning and neurodegenerative diseases, presumably via its link to PI3K activity." (PMID 34838047, 2021). "For this reason, several human hereditary and neurodegenerative diseases caused by disturbances in the functioning of the endo-lysosmal compartment are linked with TLR4 hyperactivation and inflammation contributing substantially to their pathogenesis." (PMID 33057840, 2021). "In previous studies, the association of toll-like receptor-4 (TLR4) with learning and memory processes, stress-related adaptations, and neurodegenerative diseases was observed." (PMID 33235706, 2020). "Accumulating evidence has indicated that the microglial Toll-like receptor 4 (TLR4) and autophagy are implicated in neurodegenerative diseases, but their relationship and role in neuropathic pain remain unclear." (PMID 29486776, 2018). "TLR4 is a critical component not only of the innate immune system but also the central nervous system, and is implicated in the regulation of neuropathic pain as well as in neurodegenerative diseases." (PMID 26909014, 2016). "It is associated with both neuroprotective and neurotoxic effects, neuropathic pain, neurodegenerative diseases developmental and adult neuroplasticity, and adult hippocampal neurogenesis; loss of TLR4 increases adult NPC proliferation and neuronal differentiation." (PMID 26909014, 2016). "Because inflammatory bacterial LPS induces microglial activation via the toll-like receptor (TLR)-4 pathway to cause neurological diseases, the effect of inhibiting LPS-induced microglial inflammatory responses is widely used to screen active substances for neurodegenerative diseases." (PMID 40566636, 2025). "Because TLR4 activation causes neurodegeneration, and several neurodegenerative diseases (e.g. AD, ALS and MS) are associated with abnormal TLR4 function, collectively, our data suggest that IH-induced TLR4 upregulation may play a previously unrecognized role in many CNS disorders." (PMID 24324707, 2013). "The main receptors for HMGB1 on the surface of macrophages are TLR-2 and TLR-4, with TLR-4 playing a crucial role in neurodegenerative diseases." (PMID 40385486, 2025). "In neuroinflammatory disorders, such as neurodegenerative diseases and neuropathic pain, TLR4/MD2 activation in microglia and astrocytes contributes to neuronal damage." (PMID 39976020, 2025). "Signaling through Toll-like receptor-4 can also mediate autoimmunity and neuroinflammatory activity in the context of neurodegenerative diseases." (PMID 40270596, 2025). "Nrf2 is a negative regulator of ferroptosis and protects against neurodegenerative diseases via affecting HO-1, Toll-like receptor 4 (TLR4), and the NF-κB pathway." (PMID 39050756, 2024). "LPS induces neuroinflammation via toll-like receptor 4 (TLR4) and is used as a standard neuroinflammatory model, but LPS is also directly implicated in neurodegenerative disease." (PMID 38550989, 2024).
neurodegenerative disease (continued). "The inhibitory effect of 206 was found to be regulated by the inactivation of the NF-κB, MAPK, and TLR4/MyD88 signaling pathways, indicating that 206 presented potential anti-inflammatory candidates for the treatment of neurodegenerative diseases." (PMID 39452841, 2024). "The expression levels of TLR2 and TLR4 were found to be upregulated in the brains of patients with AD and other neurodegenerative diseases such as PD." (PMID 39408923, 2024). "The inhibitory effect of 152 was found to be regulated by the inactivation of the NF-κB, MAPK, and TLR4/MyD88 signaling pathways, indicating that 152 presented potential anti-inflammatory candidates for the treatment of neurodegenerative diseases." (PMID 39452841, 2024). "Potential INFG and TLR4-mediated neuroinflammation, especially over a prolonged period, can lead to neurodegenerative disease." (PMID 39728916, 2024). "The inhibitory effect of 163 was regulated by the inactivation of the NF-κB, MAPK, and TLR4/MyD88 signaling pathways, indicating that 163 is potential anti-inflammatory candidate for the treatment of neurodegenerative diseases." (PMID 39452841, 2024). "Among the 13 TLRs in mammals, the Toll-like receptor 4 (TLR4) has been well studied in neurodegenerative disease." (PMID 34777683, 2021). "Of the many PAMPs and DAMPS that can activate TLR4, some have particular relevance to neurodegenerative disease such as amyloid-β (Aβ), α-synuclein and galectin-3 (described in further detail below)." (PMID 32709045, 2020). "TLR4 is member of Toll-like receptor family that mediates microglial activation in neurodegenerative diseases, including PD." (PMID 33167342, 2020). "Inhibition of TLR4 activation and signaling is beneficial in several animal models of neurodegenerative disease." (PMID 32709045, 2020). "Since this was the first time TAK-242 was used in a neurodegenerative disease model and the previous data regarding TLR4 antagonism in ALS are limited, we chose the dosage and administration schedule based on the limited data in the literature." (PMID 28763002, 2017). "In this study, we used TLR2 and TLR4 double knockout mice to investigate their role in vessel regression and degeneration, which is the vital pathological change in numerous degenerative diseases." (PMID 27297042, 2016). "It has been demonstrated that TLR4-mediated activation of NF-κB signaling pathway plays an important role in the neuroinflammatory responses and various neurodegenerative diseases." (PMID 26389923, 2015). "Several studies have reported that TLR4-dependent activation of microglia and astrocytes is involved in neurodegenerative diseases." (PMID 25898017, 2015). "Microglia are involved in glaucomatous and other neurodegenerative disease pathology and express high levels of TLR4." (PMID 25180891, 2014). "TLR4 as a target to modify the progression of neurodegenerative diseases proves to be a complex issue." (PMID 23108585, 2013). "Similarly, the role of Toll-Like Receptor 4 (TLR4) in neurodegenerative diseases is not well understood." (PMID 39062196, 2024). "In addition, as microglia widely express Nrf2 and TLR4, and TLR4 expression increases lead to the activation of microglia, we do not observe the expressions of Nrf2 and TLR4 in the microglia in neurodegenerative disease." (PMID 39050756, 2024). "Indeed, TLR4-dependent activation of microglia, which is responsible for persistent neuroinflammation, is well documented in a variety of neurodegenerative diseases, including PD." (PMID 37048085, 2023). "The TLR4/MD-2 complex interacts with LPS, allowing the induction of a downstream signaling cascade, which may contribute to the worsening of neurodegenerative diseases." (PMID 36129673, 2022). "At the early stages of the development of neurodegenerative diseases, activation of TLR4 may be beneficial for the clearance of β-amyloid (AD) and α-synuclein (PD) and can prevent accumulation of their aggregates characteristic for these diseases." (PMID 33057840, 2021).
neurodegenerative disease (continued). "In contrast, there are insufficient data regarding TLR4 dependent or independent cytokine effects and polyphenols' role on them in the progression of neurodegenerative diseases, while abundant investigation has been made regarding the role of cytokines in the pathogenesis of the same disorders." (PMID 31134076, 2019). "Based on these, GPS may be effective in inhibiting the progress of neurodegenerative diseases by improving memory functions due to its anti-inflammatory activities and appropriate modulation of NF-κB/iNOS/TLR4/BDNF." (PMID 30018656, 2018). "TLR4 is the major receptor of LPS and inhibition of TLR4 signaling pathway could attenuate neurodegenerative diseases." (PMID 29670526, 2018). "Our data is consistent with the report and further demonstrates an exacerbated crosstalk between Aβo and TLR4 on [Ca2+] responses and cell death in aged hippocampal neurons, which might be relevant to the pathogenesis of age-related neurodegenerative diseases." (PMID 28143556, 2017). "The Sur1-Trpm4 channel thus may be an important treatment target in degenerative diseases of the CNS mediated by TLR4-activated microglia." (PMID 27246103, 2016). "TLR4 is also upregulated in the CNS in many injuries and neurodegenerative disease processes." (PMID 24324707, 2013). "We used a model of selective activation of CD14/TLR4 co-receptors that is now appreciated to initiate innate immune response to endogenous ligands relevant to neurodegenerative diseases such as Aβ fibrils as well as peptides and neoantigens expressed by apoptotic cells." (PMID 16603079, 2006). "Furthermore, another experimental study conducted on Male Wistar rats indicated that vitamin D has the potential to prevent or treat neurodegenerative diseases by suppressing the TLR4/MyD88/NF-κB pathway, which is known to play a crucial role in the development of myocardial inflammation." (PMID 38920563, 2024). "Therefore, the modulation of TLR4 signalling could be a potential therapeutic target in neurodegenerative diseases." (PMID 37107183, 2023). "Inhibition of TLR4 expression for regulation of microglial polarization from the M1 to the M2 phenotype could prove valuable in the development of therapeutic and preventive strategies against neurodegenerative diseases." (PMID 38001534, 2023). "In summary, the involvement of TLR4-triggered signaling in the development and progression of multiple diseases is often linked with its disturbed trafficking through the endo-lysosomal compartment, as demonstrated for LSD and strongly suggested for neurodegenerative diseases." (PMID 33057840, 2021). "Interestingly, this TLR4 antagonist induced a rod microglia shape, a type of morphology found in severe pathological situations such as traumatic brain injury, infections, or neurodegenerative diseases." (PMID 31906991, 2020). "Therefore, blocking of TLR4 signaling could be helpful in reducing neuroinflammation in neurodegenerative diseases." (PMID 30046279, 2018). "In this framework, TLR4 targeting could represent a successful means to manipulate macrophages and glial cells activation and the development of molecules acting on TLR4 could represent new disease-modifying therapeutic agents for the treatment of I/R injury or for neurodegenerative diseases." (PMID 27293318, 2016). "Thus, the finding that the MC4R agonist can decrease microglial TLR4 expression suggests that melanocortins could be useful for reducing TLR4-mediated neurotoxicity in neurodegenerative diseases." (PMID 27359332, 2016). "Therefore, our results indicate that Mn3O4 nanozymes can not only inhibit LPS-induced TLR4 upregulation, but also promote the transition of microglia from M1 to M2 phenotype, thus highlighting its neuroprotective potential and therapeutic applicability in neurodegenerative diseases." (PMID 40756364, 2025).
neurodegenerative disease (continued). "LPS is a potent inducer of the inflammatory process by triggering of glial cells mainly through Toll-like receptor 4 (TLR4), which in turn produces proinflammatory cytokines, reactive oxygen species (ROS), and NO, leading to various neurodegenerative diseases." (PMID 32596307, 2020). "Taken together, these studies indicated that PRDX6 inhibits neurogenesis of neural stem cells through downregulation of WDFY1-mediated TLR4 signaling pathway and suggest that the inhibitory effect of PRDX6 on neurogenesis plays a role in the development of neurodegenerative disease." (PMID 30097850, 2019).